ABCC8 (ATP binding cassette subfamily C member 8)
Diseases named in the same sentence as ABCC8 in open-access papers (continued):
Sharing a sentence is not in itself a finding about the gene and the disease.
type 2 diabetes (continued). "Of the 132 type 2 diabetes Knowledge Portal effector genes, we identified 18 (14%) as candidate effector genes for at least one phenotype, including ABCC8, KCNJ11, NKX2–2, G6PC2, PAM, HNF4A, SLC30A8, RFX6, PCSK1, and GLIS3." (PMID 37333221, 2023). "We thus aimed to develop genetic instruments for the targets of five approved type 2 diabetes medications with known mechanisms of action (sulfonylurea receptor 1 [ATP binding cassette subfamily C member 8 (ABCC8)], PPARG, SGLT2, DPP4 and GLP1R)." (PMID 37171501, 2023). "Among these effector genes are ABCC8, KCNJ11, PDX1, ADCY5, and KCNQ1, which are recognized as pancreatic β-cell genes strongly associated with type 2 diabetes." (PMID 34425882, 2021). "A study also characterized novel mutations in ABCC8 and KCNJ11 in the Russian population, which were novel loci for susceptibility to both type II diabetes and altered insulin secretion." (PMID 25871929, 2015). "In detail, Mafa, Ins2, Abcc8 are from pathway MMU4930 (Type-II diabetes mellitus)." (PMID 39789452, 2025). "The identified genes were involved in processes such as protein localization (ENSSSCG00000041063, ADIPOQ, ABCC8), enzyme-linked receptor protein signaling pathway (PLCE1, ADIPOQ), organic substance transport (ENSSSCG00000041063, ADIPOQ, ABCC8), and type II diabetes mellitus (ADIPOQ, ABCC8)." (PMID 40819340, 2025). "Genetic variants associated with glycated hemoglobin (HbA1c), Type 2 Diabetes (T2D), and antidiabetic drug targets (KCNJ11, ABCC8, PPARG, INSR, GLP1R, SLC5A2, and DPP4) were sourced from genome-wide association studies in the UK Biobank and the DIAMANTE consortium." (PMID 39640975, 2024). "The ABCC8 promoter is linked to a distal intergenic GWAS SNP rs1557765 (body mass index) as well as three KCNJ11 intronic GWAS SNPs rs5215, rs5219, and rs757110 (type 2 diabetes) by pcHi-C data." (PMID 34425882, 2021). "Interestingly, CRISPR-based genome editing techniques were found to detect changes in ABCC8 and SUR1 expression levels in type 2 diabetes, suggesting that gene editing could be useful in diagnosing and treating KATP channel mutations in the future." (PMID 35837280, 2022). "CYP2C9 encodes sulfonylurea metabolizing cytochrome P450 isoenzyme 2C9, ABCC8 and KCNJ11 genes encode proteins constituting ATP-sensitive K+ channel which is a therapeutic target for sulfonylureas, and TCF7L2 is a gene with the strongest association with type 2 diabetes." (PMID 24324494, 2013). "Compared with all cell types, beta cells had the most genes with time–glucose interaction effects, featuring several well-established type 2 diabetes genes, including INS, ABCC8, SLC30A8 and PCBD1." (PMID 38967666, 2024). "We identify many genes with a well-defined role in relationship to type 2 diabetes (e.g., ABCC8, SLC30A8), including 18 of the 132 type 2 diabetes effector genes from the Type 2 Diabetes Knowledge Portal." (PMID 37333221, 2023). "Suggestive association was also reported between the human homologue of the trans-mediated renal eQTL gene Abcc8 (LOD=4.47, P=0.007) and diabetic nephropathy in patients with type 2 diabetes." (PMID 31213483, 2019). "Hypoglycaemia, hyperinsulinaemic (C1864903) and Diabetes, type 2 (C0011860) were connected through the genes HNF1A, ABCC8, HNF4A, and GCK, as well as the KEGG pathway Type II Diabetes Mellitus." (PMID 30255817, 2018). "Despite the absence of monoclonal antibodies against known type-2 diabetes small molecule targets ABCC8, ABCC9, DPP4, and KCNJ11, these genes demonstrated AB tractability estimates greater than 60%, along with interleukin receptors IL4R and IL17RA." (PMID 37225853, 2023). "In type II diabetes mellitus, insulin secretion, integration of energy metabolism pathways, KCNJ11, and ABCC8 were the common targets, which may be regulated by XSN." (PMID 31607935, 2019).
MODY (43 papers, 2008 to 2026). "Pathogenic variants were also identified in genes associated with MODY (maturity-onset diabetes of the young), including ABCC8, GCK, KCNJ11, and WFS1." (PMID 40149731, 2025). "The identification of pathogenic variants in genes such as GCK, HNF1A, and ABCC8 highlights their significance in MODY’s molecular etiology within the Russian population." (PMID 39859454, 2025). "This included a novel low-frequency missense variant in the ABCC8 gene, a gene known to be involved in congenital hyperinsulinism, neonatal diabetes mellitus and MODY, that was estimated to be responsible for a 170 g increase in birthweight amongst carriers." (PMID 40210729, 2025). "In the present study, we have described two heterozygous missense mutations in ABCC8 in clinically defined MODY probands using exome sequencing and conducted a pedigree co-segregation study." (PMID 39556225, 2024). "According to the literature, the prevalence of MODY owing to ABCC8 mutations ranges from 0.9 to 3.3% among clinically suspected MODY cohorts, possibly equal to 30–50 cases / 1 million individuals." (PMID 38980630, 2024). "In this study, we have detected two previously reported mutations, V357I and R1393H, in ABCC8 from two families with clinically suspected MODY." (PMID 39556225, 2024). "The heterozygous missense mutations V357I and R1393H in ABCC8 were found in probands of two unrelated MODY pedigrees, which co-segregated with the hyperglycemic phenotypes in these two pedigrees." (PMID 39556225, 2024). "For the CEL, PDX1, INS, KCNJ11 and ABCC8 genes, MODY is caused only by specific variants resulting in dominant‐negative/gain of function effects; null variants in these genes do not cause MODY." (PMID 35445424, 2022). "The ABCC8 gene is responsible for at least 1% of MODY cases in the literature and there are about 700 pathogenic variants of the ABCC8 gene in the HGMD database, with more than half of them being missense and nonsense variations." (PMID 36361703, 2022). "This study reports a novel missense variant of the ABCC8 gene in a Chinese family with suspected MODY." (PMID 35002955, 2021). "One novel missense variant c.1432G>A (p.A478T) in exon 9 of the ABCC8 gene was detected in the proband with suspected MODY." (PMID 35002955, 2021). "There are more than 30 families reported worldwide to carry the heterozygous variants of ABCC8 in MODY." (PMID 35002955, 2021). "In conclusion, our study reports that HNF1A and ABCC8 are among the most frequently mutated MODY genes in south India." (PMID 29439679, 2018). "Further sequencing studies of unselected MODY patients will elucidate if ABCC8 is a more common cause of MODY than previously anticipated." (PMID 22662265, 2012). "In summary, we have identified two ABCC8 mutations in patients with clinically suspected MODY." (PMID 39556225, 2024). "We have described two pathogenic missense mutations in ABCC8 in Chinese families with MODY." (PMID 39556225, 2024). "We did not detect any specific clinical features of MODY among patients carrying pathogenic variants of ABCC8, thereby confirming the need for genetic testing of patients with a MODY phenotype using NGS for correct diagnosis and treatment as well as for counseling the patients’ relatives." (PMID 36836406, 2023). "Mutations in KCNJ11 or ABCC8 that increase the opening probability of the channel hyperpolarise the beta cell membrane and inhibit insulin secretion, causing either neonatal diabetes or MODY." (PMID 35618782, 2022). "Our findings showed HNF1A and ABCC8 to be the most frequently mutated MODY genes in south India." (PMID 29439679, 2018). "The large size of ABCC8 makes it less amenable to Sanger-based mutation screening, which may underestimate the role of this gene in MODY." (PMID 22662265, 2012).
MODY (continued). "A separate study analyzing a panel of 14 MODY-associated genes in 178 patients with a MODY phenotype from Western Siberia identified mutations in HNF4A, GCK, HNF1A, and ABCC8 genes in 38 patients." (PMID 39859454, 2025). "Mutations in seven of these genes, including ABCC8, GCK, HNF1B, INS, KCNJ11, NEUROD1, and PDX1, are implicated in both NDM and MODY." (PMID 39859454, 2025). "A comprehensive analysis of MODY in sub-Saharan Africa revealed significant heterogeneity in MODY-related gene variants, with novel mutations identified in GCK, HNF1A, and ABCC8 genes." (PMID 39859454, 2025). "Features against a diagnosis of ABCC8-MODY are: (i) onset in adulthood; (ii) uncertain pathogenicity or likely benign nature of the ABCC8 mutations; (iii) good glycemic control without sulphonylurea or insulin." (PMID 38980630, 2024). "Based on all the previous information, MODY was suspected, and genetic testing was done, which showed rare variants in the BLK and ABCC8 genes and suggested a co-occurrence of MODY11 and MODY12." (PMID 39391454, 2024). "Three MODY subtypes are associated with mutations in hepatocyte nuclear factor (HNF) transcription factors, and two others are associated with mutations in ABCC8 and KCNJ11, which encode subunits of the ATP-dependent potassium channel in pancreatic beta cells." (PMID 39902162, 2024). "Of the 89 eDia3 patients, 10 (11.2%) carried likely pathogenic variants in genes (KLF11, GCK, ABCC8, PAX4, BLK and HNF1A) of MODY." (PMID 35921062, 2022). "Some MODY subtypes (e.g., ABCC8, KCNJ11, HNF1α, and HNF4α MODY) are manageable through KATP inhibition — i.e., sulfonylurea use." (PMID 34032641, 2021). "Fourteen subtypes of MODY have been diagnosed so far, of which MODY12 is caused by mutation of the ABCC8 (ATP Binding Cassette Subfamily C Member 8) gene, which is rarely reported in China." (PMID 33013711, 2020). "ABCC8 mutations can cause MODY in patients whose clinical features are similar to those with HNF1A/4AMODY, and some patients with ABCC8 mutations were able to change from insulin to oral glibenclamide therapy, which means that patients with ABCC8presented with T2DM-like phenotypes." (PMID 35992135, 2022). "To analyze the frequencies of the carriers of such mutations in our cohort, we analyzed genes (HNF1A, HNF4A, HNF1B, INS, ABCC8, and KCNJ11) in which a significant number of missense mutations have previously been reported in MODY, neonatal diabetes mellitus, or early onset diabetes." (PMID 29207974, 2017). "Therefore, despite its rare occurrence, the detection of ABCC8-realted MODY by genetic testing may help target patients for SU therapy." (PMID 39556225, 2024). "Previous studies have shown that it modulates the expression of several MODY genes, including insulin, GCK, ABCC8, PDX1, and PAX4." (PMID 40148250, 2025). "The mechanisms underlying MODY include β cell KATP channel dysfunction (e.g., KCNJ11 [MODY13] or ABCC8 [MODY12] mutations); however, no other β cell channelopathies have been associated with MODY to date." (PMID 34032641, 2021). "Although ABCCB-MODY is considered rare, our results were unexpected in that the ABCCB gene had the largest number of six pathogenic variants, possibly because ABCC8 is a large 39-exon gene that does not allow routine Sanger sequencing." (PMID 37327085, 2023). "In a recent study, among 16 patients with MODY who were offered treatment switch after genetic diagnosis, nine (six HNF1A, three KCNJ11) were stably switched from insulin to oral sulfonylurea but seven (three HNF4A, two ABCC8 and one each HNF1A and KCNJ11) had to restart insulin." (PMID 35618782, 2022).
Hypoglycemia (39 papers, 2008 to 2026). A decreased concentration of glucose in the blood. "GCK: A de novo variant [p.(Ala456Val)] in GCK that coexisted with a heterozygous paternal ABCC8 variant of uncertain significance [p.(Gly505Cys)] was discovered in 1 macrosomic proband with hypoglycemia (0.1 mmol/L) on the first day of life." (PMID 38963811, 2025). "Although most ABCC8 variants caused immediate disease onset with severe hypoglycemia and were diazoxide-unresponsive, 8 probands had a heterozygous, apparently dominant variant with milder phenotype." (PMID 38963811, 2025). "Loss-of-function mutations in the large regulatory SUR1 subunit encoded by ABCC8 are the most common causes of severe persistent hypoglycemia in infants and children seen in the rare disease congenital hyperinsulinism." (PMID 41022322, 2025). "A newborn had hypoglycemia at birth and was diagnosed with focal HI due to a paternally inherited recessive ABCC8 variant." (PMID 39895985, 2024). "In Family 7, the proband's mother reported undiagnosed symptoms of hypoglycemia in herself and her brother; both were found to carry the mutation identified in the proband (ABCC8: p.Glu1517Gly)." (PMID 31464105, 2019). "While the maternal uncle denied any symptoms of hypoglycemia, his oPTT revealed an abnormal hypoglycemic response, reconfirming that ABCC8 p.Val715Met was a pathogenic dominant mutation." (PMID 31464105, 2019). "As hypoglycemia due to metformin is very rare, it is tempting to speculate that the identified ABCC8 variant may be involved." (PMID 38980630, 2024). "A genetic consultation was requested, which recommended molecular genetic testing (gene panel for hypoglycemia), later performed at the Invitae laboratory, which identified a heterozygous ABCC8 c.1792C>T (p.Arg598*) mutation present in the child and his father." (PMID 38791571, 2024). "We report two cases of persistent neonatal hypoglycemia associated with mutations in the KCNJ11 and ABCC8 genes, encoding the Kir6.2 and SUR1 subunits of the adenosine triphosphate-sensitive potassium channel." (PMID 41869142, 2026). "In turn, Genetic variants in ABCC8 (SUR1) and KCNJ11 (Kir6.2) affect the function of ATP-sensitive potassium channels, modulating drug efficacy and the risk of hypoglycemia." (PMID 40395625, 2025). "Pathogenic mutations in the ABCC8 gene cause autosomal dominant and recessive FHI (OMIM 256450) and dominant leucine-sensitive hypoglycemia of infancy (OMIM 240800)." (PMID 38791571, 2024). "Congenital hyperinsulinism (CHI), a rare genetic disorder related to mutations in sulfonylurea receptor 1 (SUR1), encoded by ABCC8, is characterized by excessive insulin secretion and hypoglycemia." (PMID 33751396, 2022). "Three other studies investigated association between two strongly linked non-synonymous polymorphisms, S1369A (rs757110) and E23K (rs5219), in the ABCC8 and KCNJ11 genes, respectively with hypoglycemia." (PMID 34194474, 2021). "Sixteen family members carried the ABCC8 or KCNJ11 mutations; only two had hypoglycemia detected at birth and four others reported symptoms of hypoglycemia." (PMID 31464105, 2019). "Dominant inactivating ABCC8 and KCNJ11 mutations are less frequent, but are usually associated with a milder form of hypoglycaemia that is responsive to diazoxide therapy." (PMID 20573158, 2011). "In the second case, the patient’s father presented the same ABCC8 (Arg598Ter) heterozygous mutation as the child but did not present symptoms of hypoglycemia." (PMID 38791571, 2024). "Three of our patients (Patient 11 with a heterozygous ABCC8 variant, patient 16 with a maternally inherited INS variant, and patient 30 with a heterozygous GCK variant) presented with hypoglycemia in the neonatal period (patient 11 presented with hypoglycemic coma)." (PMID 36398453, 2023). "Ser1369Ala variant in ABCC8 does not affect the response to sulfonylurea treatment and so, is not a major player in the etiology of severe hypoglycemia." (PMID 34194474, 2021).
Hypoglycemia (continued). "Consistent with this notion, we found that GE-ERαvlVMH neurons express high levels of Abcc8 (encoding the KATP channel subunit, Sur1) and display elevated KATP currents in response to hypoglycemia; blockade of KATP currents abolishes the hypoglycemia-induced inhibition in these neurons." (PMID 32358493, 2020). "This gene is responsible for the clinical form of hypoglycemia associated with high levels of serum ammonia, and is also the major gene affected in cases in which no mutations are detected in genes ABCC8 and KCNJ11." (PMID 25972930, 2015). "Two out of three patients with ABCC8 mutations underwent pancreatectomy because of lack of response to treatment and hypoglycemia was reported to occur also post-operatively." (PMID 24932607, 2014). "Notably, GI-ERαvlVMH neurons express minimal Abcc8, and hypoglycemia does not enhance KATP currents in these neurons." (PMID 32358493, 2020).